ZNF530 (zinc finger protein 530)
Description:
May be involved in transcriptional regulation.
Synonyms: KIAA1508
Tractability: PROTAC: ubiquitination databases record sites on it.
Gene: Protein-coding gene on chromosome 19 (57,599,880 to 57,612,722, forward strand). Ensembl gene ENSG00000183647.
Subcellular location: Nucleus
Subcellular location (Human Protein Atlas): Vesicles
Pathways (Reactome):
Gene expression (Transcription): Generic Transcription Pathway
Gene Ontology:
Molecular function: DNA-binding transcription factor activity, RNA polymerase II-specific; RNA polymerase II cis-regulatory region sequence-specific DNA binding; DNA-binding transcription repressor activity, RNA polymerase II-specific; sequence-specific DNA binding
Biological process: regulation of transcription by RNA polymerase II; negative regulation of transcription by RNA polymerase II; regulation of DNA-templated transcription
Cellular component: nucleus; nucleoplasm
Genetic constraint (gnomAD): Loss-of-function variants: 3 observed, 2.24 expected, observed/expected ratio (o/e) 1.34, 90% interval 0.53 to 1.92. That is too few expected variants to judge how well the gene tolerates losing a copy. Missense variants: 609 observed, 694.92 expected, observed/expected ratio (o/e) 0.88, 90% interval 0.82 to 0.94. Synonymous variants: 227 observed, 242.84 expected, observed/expected ratio (o/e) 0.93, 90% interval 0.84 to 1.04.
Homologues: Orthologues: chimpanzee ZNF530 (99% identical), macaque ZNF530 (95% identical). Paralogues in human: ZNF416 (49% identical), ZNF17 (47% identical), ZNF776 (43% identical), ZNF417 (42% identical), ZNF587 (42% identical), ZNF287 (41% identical), ZNF34 (38% identical), ZKSCAN7 (37% identical), ZNF285 (36% identical), ZNF527 (36% identical), ZNF547 (36% identical), ZNF852 (36% identical), and 38 more.
Diseases named in the same sentence as ZNF530 in open-access papers:
ZNF530 is named in the same sentence as 1 disease in open-access papers, as found by Europe PMC text mining. Sharing a sentence is not in itself a finding about the gene and the disease. The quoted sentences say what the papers report.
cancer (2 papers, 2021). A tumor composed of atypical neoplastic, often pleomorphic cells that invade other tissues. "Finally, OV_sBRCA2 was characterized by the up-regulation of zinc finger proteins (ZNF613, ZNF329, ZNF530, ZNF347), a gene family known to be involved in pathways of carcinogenesis, cancer progression, and metastasis formation." (PMID 33525353, 2021).